RNU6-56P (RNA, U6 small nuclear 56, pseudogene)
Synonyms: RNU6-56
Gene: Small nuclear RNA gene on chromosome 13 (38,779,424 to 38,779,516, forward strand). Ensembl gene ENSG00000252795.
Homologues: Orthologues: chimpanzee U6 (97% identical), macaque U6 (77% identical), pig U6 (73% identical). Paralogues in human: RNU6-12P (84% identical), RNU6-13P (84% identical), RNU6-19P (84% identical), RNU6-31P (84% identical), RNU6-32P (84% identical), RNU6-536P (84% identical), RNU6-820P (84% identical), RNU6-1 (83% identical), RNU6-154P (83% identical), RNU6-15P (83% identical), RNU6-166P (83% identical), RNU6-16P (83% identical), and 1283 more.